DPF2 (double PHD fingers 2)
Description:
Plays an active role in transcriptional regulation by binding modified histones H3 and H4. Is a negative regulator of myeloid differentiation of hematopoietic progenitor cells. Might also have a role in the development and maturation of lymphoid cells (By similarity). Involved in the regulation of non-canonical NF-kappa-B pathway.
Synonyms: BAF45D; REQ; UBID4; ubi-d4; SMARCG2; CSS7
Tractability: PROTAC: UniProt records ubiquitination sites on it; ubiquitination databases record sites on it; its protein half-life has been measured.
Gene: Protein-coding gene on chromosome 11 (65,333,821 to 65,354,262, forward strand). Ensembl gene ENSG00000133884.
Subcellular location: Nucleus; Cytoplasm
Subcellular location (Human Protein Atlas): Nucleoplasm; Centrosome; Cytosol; Vesicles
Pathways (Reactome):
Chromatin organization: Formation of neuronal progenitor and neuronal BAF (npBAF and nBAF); Formation of the canonical BAF (cBAF) complex; Formation of the embryonic stem cell BAF (esBAF) complex
Developmental Biology: Regulation of MITF-M-dependent genes involved in pigmentation
Gene expression (Transcription): Regulation of endogenous retroelements by Piwi-interacting RNAs (piRNAs)
Gene Ontology:
Molecular function: histone H3K14ac reader activity; histone H3K9me2/3 reader activity; histone H4K16ac reader activity; protein binding; transcription coregulator activity; transcription corepressor activity
Biological process: negative regulation of myeloid progenitor cell differentiation; apoptotic process; apoptotic signaling pathway; chromatin remodeling; negative regulation of transcription by RNA polymerase II; positive regulation of double-strand break repair; positive regulation of stem cell population maintenance; regulation of DNA-templated transcription; regulation of G0 to G1 transition; regulation of G1/S transition of mitotic cell cycle; regulation of mitotic metaphase/anaphase transition; regulation of nucleotide-excision repair; regulation of transcription by RNA polymerase II
Cellular component: chromatin; cytoplasm; cytosol; nucleoplasm; nucleus; SWI/SNF complex
Genetic constraint (gnomAD): Loss-of-function variants: 10 observed, 59.16 expected, observed/expected ratio (o/e) 0.17, 90% interval 0.1 to 0.29. The upper end of that interval is the gene's LOEUF score, 0.29, which puts it in group 1 of 6, group 1 being the genes least tolerant of losing a copy. Missense variants: 315 observed, 526.07 expected, observed/expected ratio (o/e) 0.6, 90% interval 0.55 to 0.66. Synonymous variants: 189 observed, 198.73 expected, observed/expected ratio (o/e) 0.95, 90% interval 0.84 to 1.07.
Gene-disease validity (ClinGen):
ClinGen rates the evidence that DPF2 causes each of these diseases.
Coffin-Siris syndrome (autosomal dominant): Definitive. Coffin-Siris syndrome (CSS) is a rare congenital multi-systemic genetic disorder characterized by aplasia or hypoplasia of the distal phalanx or nail of the fifth digit, developmental delay, intellectual disability, coarse facial features, and other variable clinical manifestations.
Homologues: Orthologues: chimpanzee DPF2 (99% identical), guinea pig DPF2 (99% identical), pig DPF2 (99% identical), rat Dpf2 (99% identical), mouse Dpf2 (98% identical), dog DPF2 (98% identical), tropical clawed frog dpf2 (86% identical), zebrafish dpf2 (80% identical), rabbit DPF2 (79% identical), zebrafish dpf2l (77% identical), Drosophila melanogaster d4 (43% identical), Caenorhabditis elegans dpff-1 (33% identical), and 1 more. Paralogues in human: DPF3 (62% identical), DPF1 (60% identical), KAT6A (23% identical), KAT6B (22% identical), RSF1 (21% identical), KAT7 (16% identical), KAT5 (14% identical), KAT8 (13% identical), PHF10 (9% identical).
Diseases named in the same sentence as DPF2 in open-access papers:
DPF2 is named in the same sentence as 31 diseases in open-access papers, as found by Europe PMC text mining. Sharing a sentence is not in itself a finding about the gene and the disease. The quoted sentences say what the papers report.
leukaemia (2 papers, 2015 to 2023). "Here we further explore the role of SMARCA4 and the two SWI/SNF subunits SMARCD2/BAF60B and DPF2/BAF45D in leukaemia." (PMID 26571505, 2015). "In order to assess the effect of SWI/SNF complex subunits Smarca4, Smarcd2 or Dpf2 depletion in leukaemia, we transduced MLL-AF9 transformed mouse spleen cells with viruses expressing shRNA target sequences against the genes of each subunit." (PMID 26571505, 2015). "Moreover, we found that some genes are also important for leukemia development (Jarid2, Metap2, Jak3, Pla2G15, Zfp384, Casp8 and Dpf2)." (PMID 37700325, 2023). "To assess the relevance of our observations in a physiological context, we transplanted sublethally-irradiated mice with MLL-AF9 cells transduced with shRNAs targeting either Smarca4, Smarcd2, Dpf2, or non-targeting control (shScr) and monitored mice for the onset of leukaemia." (PMID 26571505, 2015).
acute myeloid leukemia (1 paper, 2023). Acute myeloid leukemia (AML) is a group of neoplasms arising from precursor cells committed to the myeloid cell-line differentiation. "To define the mechanism whereby Dpf2 loss impairs NRF2-dependent gene expression, we generated acute myeloid leukemia (AML) cell lines that express doxycycline-inducible Dpf2- or shRenilla-directed shRNAs and performed RNA-Seq and ChIP-Seq." (PMID 37200093, 2023).
anemia (1 paper, 2023). A reduction in the number of red blood cells, the amount of hemoglobin, and/or the volume of packed red blood cells. "We uncovered that hematopoiesis-specific Dpf2-KO mice developed leukopenia, severe anemia, and lethal systemic inflammation characterized by histiocytic and fibrotic tissue infiltration resembling a clinical hyperinflammatory state." (PMID 37200093, 2023).
colon cancer (1 paper, 2021). "For example, the drug mesalazine, used to treat inflammatory bowel disease but with an apoptosis-inducing and chemopreventative effect in colon cancer; DTI-Voodoo predicts mesalazine to interact with five proteins with PHD-type zinc finger domain: BRPF1, TRIM33, BAZ1A, RSF1 and DPF2." (PMID 34320178, 2021).
embryonal carcinoma (1 paper, 2025). A non-seminomatous malignant germ cell tumor characterized by the presence of large germ cells with abundant cytoplasm resembling epithelial cells, geographic necrosis, high mitotic activity, and pseudoglandular and pseudopapillary structures formation. "DPF2 directly interacts with OCT4 and depletion of DPF2 leads to increased protein levels and enhanced stability of OCT4 in P19 mouse embryonal carcinoma cells and human ESC H19 cells." (PMID 40034124, 2025).
head and neck squamous cell carcinoma (1 paper, 2024). A squamous cell carcinoma that arises from any of the following anatomic sites: lip and oral cavity, nasal cavity, paranasal sinuses, pharynx, larynx, and salivary glands. "Moreover, it was also reported that most Kcr regulators, including DPF2, KAT2B, and HDAC2–3, were significantly dysregulated in patients with head and neck squamous cell carcinoma (HNSCC); this observation positively correlated with lymph-node metastasis, T stage, and histologic grade." (PMID 38315203, 2024).
hearing loss (1 paper, 2023). "With the advancement of next-generation sequencing genetic screening, mutations in other BAF/PBAF partner genes such as SMARCC2 (BAF170), SMARCG2 (DPF2) and PHF6 have been found in patients affected with CSS-like syndrome affected with hearing loss with varying degree." (PMID 36831199, 2023).
hepatocellular carcinoma (1 paper, 2024). A malignant tumor that arises from hepatocytes. "DPF2 could potentially be utilized as a biomarker for diagnosing and prognosticating hepatocellular carcinoma." (PMID 39006087, 2024).
influenza (1 paper, 2019). An acute viral infection of the respiratory tract, occurring in isolated cases, in epidemics, or in pandemics; it is caused by serologically different strains of viruses (influenzaviruses) designated A, B, and C, has a 3-day incubation period, and usually lasts for 3 to 10 days. "IRF7 and LAMP3 are members of our influenza and vaccination biologically significant gene lists, while DPF2 was statistically significant with respect to disease state." (PMID 31787983, 2019). "The mechanistic role of host expressed genes in influenza has been investigated using knockdown experiments including genes such as IRF7, LAMP3, and DPF2 which in our study were differentially expressed in either influenza, vaccine or both." (PMID 31787983, 2019).
Intellectual disability (1 paper, 2023). "SMARCA2-ATPase mutations result in severe intellectual disability cases of NCBRS, but SMARCE1-HMG and DPF2-PHD mutations are correlated to moderate-severe and mild intellectual disability phenotypes, respectively." (PMID 37500730, 2023).
Rett syndrome (1 paper, 2024). A severe neurodevelopmental disorder affecting the central nervous system. "In two children with ASD from our cohort, VUS (in DPF2 and DEAF genes) were detected, and in one child suspected of having Rett syndrome, a 15q11.2q12q13.1 duplication syndrome was identified, which correlated with the clinical data." (PMID 39678379, 2024).
viral infection (1 paper, 2025). "PBRM1 is a chromatin modulator of the SWI/SNF chromatin remodeling complex, which includes SMARCA4, SMARCB1, SMARCC1, ARID1A, DPF2, and SMARCE1, also implicated in ACE2 expression regulation and, thus, in host cell susceptibility to viral infection." (PMID 40378209, 2025).
tumor (4 papers, 2017 to 2026). "Supportive analyses using public CRC-context single-cell and spatial transcriptomic datasets further indicated heterogeneous immune-cell expression and tumor-region enrichment of DPF2." (PMID 42232179, 2026). "Notably, in three of the seven patients that carried the NMD mutations in CHD1L, DPF2 and BRD7, the genes were down-regulated in these tumor tissues while the same genes in the other patients showed significant up-regulation (FDR < 0.05)." (PMID 31429776, 2019). "In our present study using epithelial tumor cells, we showed that the CT1 peptide comprising the 84 N-terminal amino acids of either the DPF2 or DPF3 protein functions as a dominant-negative mutant." (PMID 28924147, 2017).
infection (2 papers, 2015 to 2020). The state of being infected such as from the introduction of a foreign agent such as serum, vaccine, antigenic substance or organism. "The relationship between infection possibility (P) and DPF was shown with the equation as the following: logit(P) = −5.995 + 1.776 × DPF − 0.152 × DPF2." (PMID 32695813, 2020). "In contrast, host proteins such as TRIM28 and DPF2 also migrated slower than expected in TAP-SUMO-purified samples, although their abundance in these fractions decreased with infection, suggesting a decrease in their SUMOylation that correlated with the mass spectrometry and western blot analyses." (PMID 26549460, 2015).
cancer (1 paper, 2023). A tumor composed of atypical neoplastic, often pleomorphic cells that invade other tissues. "Loss-of-function Dpf2 mutations are found in cancer and in patients with Coffin-Siris syndrome." (PMID 37200093, 2023). "DPF2 is a defining subunit of the hematopoiesis-specific BAF (SWI/SNF) chromatin-remodeling complex, and it is mutated in multiple cancers and neurological disorders." (PMID 37200093, 2023). "DPF2 also interacts with NF-κB to control immune response genes in cancer cell lines." (PMID 37200093, 2023).
genetic disorder (1 paper, 2020). "This genetic disorder is caused by de novo mutations of ARID1A (CSS2; 1p36.11; MIM 614607), ARID1B (CSS1; 6q25.3; MIM 135900), DPF2 (CSS7; 11q13.1; MIM 618027), SMARCA4 (CSS4; 19p13.2; MIM 614609), SMARCB1 (CSS3; 22q11.23; MIM 614608) or SMARCE1 (CSS5; 17q21.2; MIM 616938) genes." (PMID 32916978, 2020).
DPF2 also shares sentences with these, for which no sentence is quoted: Coffin-Siris syndrome (2 papers); neurodegenerative disease (2); CHOPS syndrome (1); colon adenocarcinoma (1); glioblastoma (1); inflammatory bowel disease (1); KBG syndrome (1); leukopenia (1); lymph node metastasis (1); neuroblastoma (1); neurological disorders (1); Nicolaides-Baraitser syndrome (1); spinal cord disease (1); spinal cord injury (1); syndromic intellectual disability (1).